BRCA2 (BRCA2 DNA repair associated)
Diseases named in the same sentence as BRCA2 in open-access papers (continued):
Sharing a sentence is not in itself a finding about the gene and the disease.
breast cancer (continued). "We demonstrate that the Tyrer-Cuzick algorithm effectively predicted breast cancer occurrence in women unaffected at the time of recruitment if they were in a family carrying a BRCA1 or BRCA2 mutation, though not otherwise." (PMID 16507150, 2006). "In this latter report they found evidence of increasing risk with increasing parity among BRCA2 mutation carriers and that BRCA1 mutation carriers with four of more children were at a significantly lower risk of developing breast cancer than nulliparous carriers." (PMID 17187672, 2006). "The results suggest that the relative risks of breast cancer associated with parity among BRCA1 and BRCA2 mutation carriers may be similar to those in the general population and that reproductive history may be used to improve risk prediction in carriers." (PMID 17187672, 2006). "Increasing age at first live birth was associated with an increased breast cancer risk among BRCA2 mutation carriers (p trend = 0.002) but not BRCA1 carriers." (PMID 17187672, 2006). "It is important to determine what these effects may be because of the increasing use of endocrine agents such as TAM for breast cancer prevention in BRCA1 and BRCA2 mutation carriers." (PMID 16538216, 2006). "The results of the second part of the study demonstrate that spontaneous abortions do not influence the risk of breast cancer among women with either a BRCA1 or BRCA2 mutation." (PMID 16563180, 2006). "One explanation could be that, compared to sporadic cases, BRCA1/BRCA2-related breast cancers, as well as breast cancers diagnosed in the context of a strong family history, are less susceptible to be detected by mammography screening." (PMID 16404417, 2006). "Compared to women who never had an abortion, BRCA2 mutation carriers who had two or more abortions had a 64% decrease in the risk of breast cancer (OR = 0.36; 95% CI 0.16–0.83; p = 0.02)." (PMID 16563180, 2006). "Carrying a BRCA1 or BRCA2 mutation is not a risk factor for spontaneous abortions and spontaneous abortions do not appear to influence the risk of breast cancer in carriers of BRCA1 or BRCA2 mutations." (PMID 16563180, 2006). "Furthermore, we also found that combined spontaneous and therapeutic abortions conferred protection against BRCA2 breast cancers." (PMID 16563180, 2006). "First-degree female relatives of breast cancer patients have an approximately two-fold increased risk over the general population, but less than 25% of this excess risk is explained by inherited mutations in known high penetrance breast cancer susceptibility genes, such as BRCA1 and BRCA2." (PMID 16685266, 2006). "The TMA contained cores from 20 BRCA1, 14 BRCA2 and 59 sporadic age-matched breast carcinomas." (PMID 16595007, 2006). "The risk of breast cancer in women who inherit a germline mutation in the BRCA1 gene can be as high as 20% by the age of 40 and 50% by the age of 50 and as high as 13% by the age of 40 and 60% by the age of 50 in BRCA2 mutation carriers." (PMID 16079000, 2005). "We have reported elsewhere that parity is a risk factor for breast cancer in BRCA2 carriers but not in BRCA1 carriers." (PMID 16168130, 2005). "In this study, CPM reduced the risk for contralateral breast cancer in BRCA1 or BRCA2 mutation carriers by 91%, independent of the impact of BPO." (PMID 16052221, 2005). "Compensation of the 1100delC defect in CHK2 by CHK1, or any other mechanism, might explain the rather low breast cancer risk associated with the CHEK2 variant, compared to that associated with truncating mutations in BRCA1 or BRCA2." (PMID 15700044, 2005). "The other BRCA2 mutation was also found in exon 11 of BRCA2 in a patient who developed the disease at the early age of 29 years, and who had no relatives affected by breast cancer." (PMID 16389418, 2005). "We asked whether there is an association between changes in body weight and the risk of breast cancer in women who carry a mutation in either breast cancer susceptibility gene, BRCA1 or BRCA2." (PMID 16168130, 2005).
breast cancer (continued). "3401delC) in the 75 selected non-BRCA1/BRCA2 breast cancer index cases." (PMID 16280053, 2005). "In spite of the high prevalence of breast cancer in the Brazilian population, there has not been any systematic study of BRCA1 and BRCA2 mutations among breast cancer patients with a family history of the disease." (PMID 16389418, 2005). "Yet, a substantial proportion of familial breast cancer cases have no identifiable BRCA1/BRCA2 germline mutations, and other, yet unidentified genetic factors underlie these cases." (PMID 15756275, 2005). "Such compensation of the 1100delC defect in CHEK2 might explain the rather low breast cancer risk associated with the CHEK2 variant, compared to that associated with truncating mutations in BRCA1 or BRCA2." (PMID 15700044, 2005). "The AR exon 1 CAG repeat polymorphism does not appear to have an effect on breast cancer risk in BRCA1 or BRCA2 mutation carriers." (PMID 15743497, 2005). "About 5–10% of all breast cancer cases occur in women with a strong family history, and in the Netherlands approximately 25% of these cases may be attributed to the BRCA1 and BRCA2 breast cancer susceptibility gene mutations." (PMID 15199386, 2004). "Additional studies, particularly of women with a family history of breast cancer who do not carry mutations in the BRCA1 or BRCA2 genes, are warranted." (PMID 15535844, 2004). "Although there are data to suggest that oral contraceptive use is associated with a small increased breast cancer risk in carriers of BRCA1 (but not BRCA2) mutations, this effect was being driven by use prior to the mid 1970s." (PMID 15545966, 2004). "For a BRCA2 carrier without any information on FH, the predicted absolute risk of breast cancer by age 60 years is 30%." (PMID 15381934, 2004). "For BRCA2, the BCLC study revealed an increased ovarian to breast cancer ratio for OCCR mutations, due to a reduced absolute risk of breast cancer." (PMID 15026808, 2004). "An increased frequency of CHEK2*1100delC was found among breast carcinoma families without BRCA1 or BRCA2 mutations, associated with an approximately two-fold increase of breast cancer risk in female carriers." (PMID 14970869, 2004). "It is highly conceivable that certain mutations may be associated with higher risks of cancer at certain sites, as seen with BRCA2." (PMID 12865922, 2003). "The effect of resveratrol on BRCA1 and BRCA2 mRNA in human breast cancer cell lines could be explained by its different properties." (PMID 12838319, 2003). "The potential role of this polymorphism was investigated in relation to breast cancer risk in Icelandic male and female carriers and noncarriers of a BRCA2 mutation." (PMID 12644832, 2003). "Here, we studied the effects of resveratrol on the expression of BRCA1 and BRCA2 in human breast cancer cell lines at the transcription level using quantitative real-time reverse transcription (RT)–PCR, and at the translation level by perfusion chromatography of the proteins." (PMID 12838319, 2003). "The breast cancer risk by age 70 years was estimated to be 49.6% for BRCA1 and 82.2% for BRCA2." (PMID 11857015, 2002). "We analysed by direct sequencing the BRCA2 gene in 29 breast cancer patients derived from 29 families with an aggregation of at least one female breast cancer diagnosed before the age of 50 years and one male stomach cancer diagnosed before the age of 55 years." (PMID 12373604, 2002). "Nine BRCA2 mutation carriers had no family history of breast or ovarian cancer, five had one relative that developed breast cancer and one had two first degree relatives diagnosed with breast cancer." (PMID 11857015, 2002). "In sporadic breast cancer, the majority of tumours are ER positive, whereas the opposite is the case in cancers diagnosed in women with high risk mutations in the BRCA1 and BRCA2 genes." (PMID 11870509, 2002).
breast cancer (continued). "The high frequency of bilateral disease in multi-case breast cancer families may be due to a familial aggregation of additional susceptibility factors modifying the penetrance of BRCA1 and BRCA2 mutations." (PMID 11556836, 2001). "We also demonstrated two BRCA1 and one BRCA2 mutations in three out of 52 (5.8%) early-onset breast cancer cases without additional family history." (PMID 10952777, 2000). "However, in other cancers, such as breast cancer, BRCA2 is a well-established oncogenic driver." (PMID 41139700, 2026). "Germline testing of the BRCA1 and BRCA2 genes (BRCA) has been well-established for more than two decades for women with invasive breast cancer (BC)." (PMID 39876688, 2025). "Importantly, knowledge of BRCA status before breast cancer diagnosis was associated with a trend toward improved DFS (in BRCA1 carriers only) and significantly better unadjusted BCSS and OS (in both BRCA1 and BRCA2 carriers)." (PMID 39993249, 2025). "Pathogenic variants (PVs) in BRCA1 and BRCA2 are causative of hereditary breast and ovarian cancer (HBOC), a hereditary syndrome associated with increased lifetime risk of breast cancer (BC) and ovarian cancer (OC)." (PMID 40649708, 2025). "Notably, a frameshift deletion in the partner and localizer of BRCA2 (PALB2), a well-established breast cancer susceptibility gene involved in HR-mediated DSBs repair, was found in a family with a history of both gastric and breast cancers, suggesting PALB2 as a novel contributor to HDGC risk." (PMID 40869030, 2025). "However, a subgroup analysis showed an association between RRSO and risk-reduction in primary breast cancer in BRCA2 P/LP variant carriers (RR 0.63; 95% CI 0.41–0.97) but not for CBC (RR 0.35; 95% CI 0.07–1.74)." (PMID 39858629, 2025). "Of note, when we analysed the ENCODE data of gene promoters in MCF7 breast cancer cells that also bind BRCA2 (BRCA1 antibody is not reported in the ENCODE database) and Kaiso, we identified a generous list of genes, though fewer than co-bind gene promoters in HCT116 cells." (PMID 40460875, 2025). "Interestingly, BRCA1 and BRCA2 are often coinherited in ovarian and breast cancers." (PMID 39985003, 2025). "We showed that there is a coordinated behavior between BRCA1 and BRCA2 in breast cancer, reflected in their expression patterns, and also that the BRCAness profile could be important in different tumor types and should be taken into consideration in patient management." (PMID 41373491, 2025). "Sanger sequencing of the coding sequences and exon–intron junctions of BRCA1 and BRCA2 on DNA from the blood samples of the patients who donated their breast cancer tissue for PDTX, had confirmed the absence of pathogenic germline mutations in both PDTX models." (PMID 40764992, 2025).
breast cancer (continued). "In addition, relatives of men with a pathogenic germline variant in one of the genes that are related to breast cancer in women (BRCA1, BRCA2, ATM, CHEK2, PALB2) might benefit from genetic testing of the index patient." (PMID 39639158, 2025). "Moreover, studies have shown texture to be able to distinguish BRCA1 and BRCA2 carriers from women of low risk of breast cancer, which is not the case for density." (PMID 39202310, 2024). "Additionally, mutations in DNAH11 have been reported in BRCA1‐ and BRCA2‐negative breast cancer families, further supporting its role in cancer predisposition." (PMID 38970307, 2024). "We show this for the BRCA2 gene, which like RB1 is one of most commonly affected cancer predisposition genes in the affected pediatric population, and in some populations has been shown to have a parent-of-origin effect with paternal origin of mutation affecting breast cancer penetrance." (PMID 39724000, 2024). "Loss-of-function mutations in the breast cancer (BC) susceptibility genes 1 and 2 (BRCA1 and BRCA2; BRCA) are associated with an increased risk of developing BC." (PMID 38112922, 2024). "The efficacy of PARPi therapy was initially demonstrated in high-grade serous ovarian cancer (referred to as OV hereafter) and breast cancer (BC), in which HRD was driven by germline pathogenic variants in either the BRCA1 or BRCA2 genes." (PMID 39055334, 2024). "This may be related to previous studies reporting that triple negative breast cancers and breast cancers arising from BRCA2 mutation carriers tend to originate from the posterior portion of the breast." (PMID 38503998, 2024). "The age-adjusted HRs for breast cancer mortality associated with entering an MRI surveillance program were 0.20 (95% CI, 0.10-0.43; P < .001) for women with BRCA1 sequence variations and 0.87 (95% CI, 0.10-17.25; P = .93) for women with BRCA2 sequence variations." (PMID 38421676, 2024). "The risk of developing breast cancer is increased by 7% to 8% in males with the BRCA2 mutation, compared to a 1% risk for males with BRCA1.6,7 BRCA2 mutations are the most common in male breast cancer; however, this mutation is not the only mutation that is tested for." (PMID 38912178, 2024). "The primary objective of this study was to determine the prevalence of GPVs in BRCA1, BRCA2, and PALB2 (B1B2P2) as well as in other breast cancer susceptibility genes (BCSGs) within a racially and ethnically diverse cohort of women with newly diagnosed breast cancer." (PMID 39226054, 2024). "Two human breast cancer genes, BRCA1 and BRCA2, and the CDK5RAP2 gene involved in the cell cycle regulation, have been linked with increased odds of mammary tumours in the English Springer Spaniel, a breed at high risk of mammary tumours which is closely related to the ECS." (PMID 38233914, 2024). "Roughly 10% of breast cancers result from inherited PVs in the BRCA1 and BRCA2 genes, most of which can be inherited in an autosomal dominant fashion as part of the Hereditary Breast and Ovarian Cancer (HBOC) syndrome and greatly increase the risk of developing breast cancer." (PMID 39682099, 2024). "No data specifically connect BRIP1 mutations with BRCA2 breast cancer." (PMID 38912178, 2024). "Thus, inherited C-terminal truncation variants in TREX1 might cause increased odds of breast cancer, similar to the common risk alleles in BRCA1 and BRCA2." (PMID 38824133, 2024). "Women who were BRCA1/BRCA2 mutation carriers and were under 45 years of age and who received risk-reducing salpingo-oophorectomy and hormonal replacement treatment did not affect their breast cancer rates." (PMID 37384143, 2023). "○ Women with a pathogenic mutation of the BRCA2 gene or other genes at moderate or high risk for breast cancer, in addition to those not tested but with first-degree relatives who are carriers should undergo mammographyannually after the diagnosis of the mutation (not before age of 30)(Category A)." (PMID 37683660, 2023).
breast cancer (continued). "Furthermore, patients with HER2-negative early breast cancer and germline BRCA1 or BRCA2 variants could also benefit from adjuvant Olaparib treatment." (PMID 38274092, 2023). "The homologous recombination (HR) repair pathway for DNA damage, particularly the BRCA1 and BRCA2 genes, has become a target for cancer therapy, with poly ADP-ribose polymerase (PARP) inhibitors showing significant outcomes in treating germline BRCA1/2 (gBRCA1/2) mutated breast cancer." (PMID 38098088, 2023). "In breast cancer cells, mutations in BRCA1 and BRCA2 differentially modulate the tumor-immune microenvironment, which may be partially due to distinct mutational and copy number profiles, resulting in differential responses to checkpoint blockade immunotherapy." (PMID 37174127, 2023). "Germline testing for breast cancer should also include the PALB2 gene, considering the frequency of pathogenic defects in the general population and because PALB2 heterozygotes should be considered for the same therapeutic regimens and clinical trials as those for BRCA1 and BRCA2 carriers." (PMID 37239058, 2023). "To investigate whether MBC and FBC risk might be at least in part due to different genes, we then examined their mutability in a population of high-risk breast cancer women without BRCA1/BRCA2/PALB2 PV/LPV detected on the same 585-gene panel analysis." (PMID 37762649, 2023). "Therefore, we aimed to assess and compare ultrasound image findings, including vascularity and elasticity, and pathologic features of BRCA1 and BRCA2 breast cancers in Japanese women based on the categories of the Japan Association of Breast and Thyroid Sonology (JABTS) guidelines." (PMID 36905492, 2023). "In addition, whether breast cancer cells have breast cancer susceptibility gene 1 (BRCA1) and BRCA2 mutations affects their responses to treatment differently." (PMID 37762330, 2023). "To study the specificity of this MBC PV/LPV profile, we examined whether variants in the same genes could be detected in a female breast cancer (FBC) cohort without BRCA1/BRCA2/PALB2 PV/LPV." (PMID 37762649, 2023). "This study evaluated the effect of age at breast cancer diagnosis and cancer family history on the risk of carrying a PV in breast cancer susceptibility genes routinely included in breast cancer predisposition multi-gene panels, ATM, BRCA1, BRCA2, CHEK2, and PALB2." (PMID 37084156, 2023). "The somatic mutational landscape and in particular the extent of BRCA-like tumour features (BRCAness) in these familial breast cancers where germline BRCA1 or BRCA2 mutations have not been identified is to a large extent unknown." (PMID 37316882, 2023). "Moreover, approximately a four-fold risk of breast cancer was reported in women with a significant family history of breast cancer but who tested negative for BRCA1 or BRCA2 variants." (PMID 37656691, 2023). "Whereas BRCA2 mutations, have been reported to play a role in neoplasia in hereditary breast and ovarian cancer (HBOC) and may be involved in up to half of hereditary breast cancer." (PMID 36717525, 2023). "This bias may be due to the fact that the most common causative gene was BRCA2, which causes HR + breast cancer, pancreatic cancer, and prostate cancer, as opposed to BRCA1, which causes triple-negative breast cancer and ovarian cancer." (PMID 36494460, 2023). "Germline BRCA2 mutations were found only in HER2-low patients in our NGS database, especially in patients with HR+ tumors, which might be a unique characteristic of HER2-low breast cancer." (PMID 37264417, 2023). "Based on the limited evidence available, there are indications that physical activity during the formative years of adolescence and young adulthood may decrease or postpone the occurrence of breast cancer in individuals carrying BRCA1 and BRCA2 P/LP germline variants." (PMID 37628558, 2023).